ARL14EP (ARF like GTPase 14 effector protein)
Description:
Through its interaction with ARL14 and MYO1E, may connect MHC class II-containing cytoplasmic vesicles to the actin network and hence controls the movement of these vesicles along the actin cytoskeleton in dendritic cells.
Synonyms: ARF7EP; C11orf46; FLJ38968; dJ299F11.1
Tractability: Antibody: its Gene Ontology location is reachable by antibodies, with high confidence. PROTAC: UniProt records ubiquitination sites on it; ubiquitination databases record sites on it; its protein half-life has been measured.
Gene: Protein-coding gene on chromosome 11 (30,323,104 to 30,338,458, forward strand). Ensembl gene ENSG00000152219.
Subcellular location: Cytoplasm
Subcellular location (Human Protein Atlas): Cytosol; Focal adhesion sites; Vesicles; Nucleoli; Nucleoplasm; Plasma membrane
Gene Ontology:
Molecular function: protein binding
Cellular component: cytosol; cytoplasm
Genetic constraint (gnomAD): Loss-of-function variants: 12 observed, 23.61 expected, observed/expected ratio (o/e) 0.51, 90% interval 0.32 to 0.82. The upper end of that interval is the gene's LOEUF score, 0.82, which puts it in group 3 of 6, group 1 being the genes least tolerant of losing a copy. Missense variants: 253 observed, 322.15 expected, observed/expected ratio (o/e) 0.79, 90% interval 0.71 to 0.87. Synonymous variants: 97 observed, 107.75 expected, observed/expected ratio (o/e) 0.9, 90% interval 0.76 to 1.07.
Homologues: Orthologues: macaque ARL14EP (100% identical), chimpanzee ARL14EP (99% identical), rabbit ARL14EP (99% identical), pig ARL14EP (98% identical), guinea pig ARL14EP (97% identical), rat Arl14ep (93% identical), mouse Arl14ep (93% identical), tropical clawed frog arl14ep (40% identical), zebrafish arl14ep (31% identical). Paralogues in human: ARL14EPL (19% identical), THAP7 (11% identical), THAP1 (10% identical), THAP3 (9% identical), THAP2 (9% identical), THAP8 (8% identical), THAP6 (5% identical).
Diseases named in the same sentence as ARL14EP in open-access papers:
ARL14EP is named in the same sentence as 8 diseases in open-access papers, as found by Europe PMC text mining. Sharing a sentence is not in itself a finding about the gene and the disease. The quoted sentences say what the papers report.
endometriosis (6 papers, 2019 to 2026). The growth of functional endometrial tissue in anatomic sites outside the uterine body. "Gene annotation implicated specific candidate genes, including ARL14EP for the endometriosis-BD link, which was further validated across SMR, MAGMA, and GCTAfastBAT analyses." (PMID 41578317, 2026). "By extending the genomic window around the consensus clusters by 2 kb to account for the promoter region, consensus clusters were found to overlap 11 endometriosis-associated SNPs across 6 genomic regions, including gene regions near FGD6, ARL14EP and CDC42." (PMID 37443771, 2023). "After combining gene-based p-values across endometriosis and migraine GWAS, we found that three genes (ARL14EP, TRIM32, and SLC35G6), were genome-wide significant." (PMID 32121467, 2020).
WAGR syndrome (2 papers, 2019 to 2022). WAGR syndrome (Wilms tumor - aniridia - genitourinary anomalies - intellectual disability mental retardation) is a rare genetic disorder characterized by an unusual complex of congenital developmental abnormalities with intellectual disability, and an increased risk of developing Wilms tumor. "ARL14EP (OMIM: 612295; ADP-ribosylation factor-like GTPase 14 effector protein), located on chromosome 11p13, is a gene involved in WAGR syndrome." (PMID 36011342, 2022).
type 2 diabetes (1 paper, 2022). "Intersecting the single-trait TWAS results across traits, we identified one gene, ARL14EP, expressed in multiple tissues of the cardiovascular system and exocrine/endocrine system, that is shared between type 2 diabetes and PCOS." (PMID 35771237, 2022).
ARL14EP also shares sentences with these, for which no sentence is quoted: aniridia (1 paper); Intellectual disability (1); migraine (1); neuroblastoma (1); Sepsis (1).